GCGR (glucagon receptor)
Diseases named in the same sentence as GCGR in open-access papers (continued):
Sharing a sentence is not in itself a finding about the gene and the disease.
Obesity (continued). "Interestingly, a recent study has reported that retatrutide, a triple agonist of glucagon receptor (GCGR), glucose-dependent insulinotropic polypeptide receptor (GIPR) and GLP-1R, alleviated tumor growth and chemotherapy resistance in obesity-associated triple-negative breast cancer." (PMID 41244507, 2025). "Meanwhile, research on the mechanism and efficacy of GLP-1R/GIPR dual agonists and GLP-1R/GIPR/GCGR triple agonists paves the way to a ground-breaking therapy specific for obesity, which suggests multi-target drugs may have more advantages than a single target." (PMID 36843578, 2023). "At present, more compounds of receptors with dual agonists are being tested, for example, GLP-1R/GR (glucagon receptor), GLP-1R/AR (amylin receptor) and GLP-1R/NPYR (peptide YY binds to neuropeptide Y receptors), and might achieve further advances in T2DM, obesity and associated conditions therapy." (PMID 37904255, 2023). "Thus “triple agonism” of GLP-1R, GIPR, and GcgR could represent a new standard for pharmaceutical intervention in obesity." (PMID 35809773, 2022). "Therefore, knowledge of the effects of glucagon receptor agonism on reproductive hormones is important for developing therapeutics for obesity; but reports in the literature about the effects of glucagon receptor agonism on the reproductive axis are conflicting." (PMID 32232363, 2020). "Other dual GLP-1R/GCGR agonists are being actively studied to treat NAFLD, with Pemvidutide (ALT-801) emerging as a promising candidate for managing obesity and MASH." (PMID 40004572, 2025). "OXM will probably redefine the landscape of obesity and metabolic therapies, providing an unparalleled physiological approach by simultaneously targeting GLP1R and GCGR." (PMID 39495024, 2025). "Another GCGR/GLP-1R dual agonist, cotadutide, has been developed for the treatment of type 2 diabetes and obesity." (PMID 38095657, 2024). "GLP-1R, GCGR and GIPR are essential regulators of glucose homeostasis and therapeutic targets for type 2 diabetes and obesity." (PMID 38346960, 2024). "Survodutide (BI 456906) is a novel subcutaneous GCGR/GLP-1R dual agonist in development for the treatment of people with type 2 diabetes, obesity and non-alcoholic steatohepatitis (NASH)." (PMID 38095657, 2024). "The results of this trial highlight the potential of the novel GCGR/GLP-1R dual agonist survodutide for the treatment of NASH, type 2 diabetes and obesity." (PMID 38095657, 2024). "DD01, a long-acting dual agonist for GLP-1R/GCGR, is also in a phase 1 clinical trial to investigate the effects on NASH, T2DM, and obesity (A Phase 1 Study of DD01 in Overweight/Obese Subjects with T2DM and NAFLD, NCT04812262, phase 1)." (PMID 37514148, 2023). "In a randomized placebo-controlled, multicenter phase 1 study, the efficacy and safety of the dual GLP-1/glucagon receptor agonist mazdutide (IBI362) at doses of 9 mg and 10 mg weekly were evaluated in subjects with overweight and obesity." (PMID 37729025, 2023). "Recently, several multi-targeting agonists of GIPR, GLP-1R, or GCGR for treating T2DM and obesity have been in clinical trials." (PMID 36843578, 2023). "Some of the most recent drug developments for T2DM and obesity are the triagonists for GLP-1R, GIPR, and GCGR (GLP-1R/GIPR/GCGR)." (PMID 36145148, 2022). "Multiple dual receptor agonists are in clinical development for the treatment of obesity, including GLP‐1/GIP and GLP‐1/glucagon receptor agonists." (PMID 34713962, 2022). "It is known that peptide 20 potently reversed metabolic disorders in rodent models of obesity and diabetes, characteristic of increased energy expenditure and elevated circulating FGF21 levels as a result of GCGR agonism." (PMID 35217653, 2022). "One of the latest approaches to develop more efficacious therapeutics against T2DM and obesity relates to dual- and tri-agonists targeting two or more of GLP-1R, glucagon receptor (GCGR), and glucose-dependent insulinotropic peptide receptor (GIPR)." (PMID 33414387, 2021).
Obesity (continued). "Multi-target peptide therapeutics targeting glucagon receptor (GCGR), glucagon-like peptide-1 receptor (GLP1R), and glucose-dependent insulinotropic polypeptide receptor (GIPR) represent a promising approach for treating diabetes and obesity." (PMID 41333850, 2025). "Therefore, development of incretin dual agonists such as the novel GCGR/GLP-1R dual agonist survodutide is an important step towards the more effective treatment of people with type 2 diabetes and obesity." (PMID 38095657, 2024). "The addition of GCGR agonism to GLP-1R agonism may therefore prove to be more efficacious in the treatment of type 2 diabetes and obesity, producing additive effects on energy intake and expenditure." (PMID 38095657, 2024). "Nonintuitively, more attention has recently shifted toward GCGR agonism partly due to its role in increasing energy expenditure to combat obesity." (PMID 38477666, 2024). "Our results are consistent with previous studies on the efficacy and safety of the GLP-1R agonists and GCGR dual agonists for the treatment of obesity and overweight in individuals with and without diabetes." (PMID 38440786, 2024). "Our findings indicate that treatment with the dual GLP-1 and glucagon receptor agonist cotadutide improves metabolic and functional parameters in the liver compared with placebo and liraglutide in patients with T2DM and overweight or obesity." (PMID 38066113, 2023). "As dual-agonism may provide superior glucoregulatory and anti-obesity effects to mono-agonists, there have been attempts to modify the peptide sequence of OXM for more balanced dual agonism for GLP-1R and GCGR." (PMID 37514148, 2023). "As alluded to above, the ability of OXM to effectively activate both GCGR and GLP-1R, thereby improving blood glucose and body weight, is attractive for the development of peptide therapeutics for obesity/T2DM, provided an appropriate receptor balance is struck." (PMID 34093449, 2021). "Two studies evaluated the efficacy and safety of JNJ-64565111, a weekly-dose GLP-1 and glucagon receptor dual agonist, in individuals with obesity without type 2 diabetes and individuals with type 2 diabetes and obesity." (PMID 34430840, 2021). "In light of the anti-obesity effect of GLP-1, these findings might be attributed to an increased level of GLP-1 in blood with reduced gastric emptying in GCGR knockout mice." (PMID 23226550, 2012). "Furthermore, several RCTs in adults with overweight or obesity have evaluated other multi-receptor drugs, such as Retatrutide, which targets GIPR/Glucagon receptor (GCGR)/GLP-1R, and Mazdutide, which targets GCGR/GLP-1R, showing promising results in both glycemic management and weight reduction." (PMID 39968298, 2025). "However, Myf5 promoter-driven deletion of GCGR in BAT did not affect diet-induced obesity or glucagon-induced energy expenditure." (PMID 40892365, 2025). "As opposed to singular incretin effects, oxyntomodulin (OXM) activates glucagon receptors (GCGR) and glucagon‐like peptide‐1 receptors (GLP1R), demonstrating a more dynamic range of effects that are more likely to align with evolving ‘health gains’ goals in obesity care." (PMID 39495024, 2025). "Currently, there are other dual GIPR/GLP-1R agonists available, such as GLP-1R/GR (glucagon receptor), GLP-1R/AR (amylin receptor), and GLP-1R/NPYR (peptide YY binds to neuropeptide Y receptors) and even triple agonists that can activate GIPR to treat obesity and T2DM." (PMID 38987789, 2024). "Since the GCGR agonists have emerged as potential therapeutic options for managing obesity, diabetes and other metabolic disorders, one intriguing development in this field is the discovery of unimolecular dual agonists that simultaneously activate both the GLP1R and the GCGR." (PMID 38093651, 2023). "Hence, bioactive peptidescotargeting GCGR and GLP-1R may remediate the blood glucose and fattyacid metabolism imbalance, tackling both diabetes and obesity to supersedecurrent monoagonist therapy." (PMID 37523325, 2023).
Obesity (continued). "In another randomized controlled trial, the dual GLP-1/glucagon receptor agonist JNJ-64565111 (efinopegdutide) was compared at doses of 5.0 mg, 7.4 mg, or 10.0 mg to placebo for 12 wk in 195 subjects with type 2 diabetes mellitus (A1c 6.5%–9.5%), and obesity (BMI 35–50 kg/m2)." (PMID 37729025, 2023). "Given emerging evidence that di- and triagonists that include glucagon receptor agonists are effective in treating obesity and dyslipidemia in rodents, nonhuman primates, and humans, it is critical to understand the tissue-specific effects of glucagon receptor action." (PMID 36002172, 2022). "Thus, the GCGR agonist approach may have utility in treating obesity and possibly other metabolic conditions such as non-alcoholic steato-hepatitis (NASH)." (PMID 35547006, 2022). "The dual GLP-1/glucagon receptor agonist JNJ-64565111 (efinopegdutide) was compared with placebo and liraglutide 3.0 mg in a 26-wk multicenter study in 474 subjects with high-grade obesity (BMI 35–50 kg/m2) without diabetes." (PMID 37729025, 2023).
diabetes (67 papers, 2011 to 2025). "The glucagon receptor (GCGR) gene is also reported as a diabetes susceptibility gene because glucagon is an essential hormone for regulating blood glucose levels." (PMID 40775340, 2025). "Although GCGR and glucagon play important roles in diabetes, the mechanisms and role of mutations still needs to be explored." (PMID 35784565, 2022). "We also elucidate the correlation between GCGR mutations in populations and the occurrence of diabetes." (PMID 35784565, 2022). "In this review, recent research on the mechanisms by which glucagon and its receptor contribute to the pathogenesis of diabetes as well as correlations between GCGR mutation rates in populations and the occurrence of diabetes are summarized." (PMID 35784565, 2022). "Genetic deficiency of glucagon receptor prevents β-cell loss in experimental diabetes induced in glucagon knock-out mice." (PMID 27192084, 2016). "The effects of ablation of glucagon actions on the development of insulin-deficient diabetes have been studied in glucagon receptor knockout mice (Gcgr−/−)." (PMID 23316165, 2012). "For example, the inclusion of GIPR targets in GLP-1R/GCGR agonists may buffer the risk of diabetes from chronic GCG receptor excitation." (PMID 40004115, 2025). "Given the heterogeneity of the disease, the importance of GCGR for diabetes susceptibility may vary among ethnicities owing to the differences in genetic and environmental factors." (PMID 35784565, 2022). "Further research is needed to explore the relationship between GCGR variants and diabetes." (PMID 35784565, 2022). "Together, these findings suggest that the contribution of GCGR to diabetes may vary and mutations in this gene play only a small role in determining the susceptibility of an individual to diabetes and the observed genetic heterogeneity of diabetes." (PMID 35784565, 2022). "The glucagon receptor is an important drug target for diabetes and metabolic disorders because of its involvement in metabolism." (PMID 40280422, 2025). "This limits the role of GCGR gene knockout in the treatment of diabetes in rodents, as it triggers a range of other metabolic issues." (PMID 39948335, 2025). "This is an unexpected result as it underscores the significant potential of GCGR in diabetes treatment." (PMID 39948335, 2025). "GCK, which encodes the β-cell glucose sensor glucokinase, was also downregulated in the diabetes cohort, as was the glucagon receptor which allows glucagon to positively influence insulin release within the paracrine environment of the islet." (PMID 40244011, 2025). "In summary, the collective evidence from various studies, including those exploring dual agonists (GLP-1R/GIPR) and tri-agonists (GLP-1R/GIPR/GCGR), demonstrates unprecedented improvements in diabetes and body weight compared to GLP-1RA treatment alone." (PMID 39145614, 2024). "Our study suggests that the glucagon receptor is a potential therapeutic target in the treatment of diabetes and dyslipidemia." (PMID 39265079, 2024). "Accordingly, genetic suppression of glucagon signaling in mice prevents diabetes and GCGR antagonism improves glycemic control in both diabetic rodents and humans." (PMID 38944125, 2024). "In fact, several GCGR/GLP-1R dual agonists are currently undergoing clinical trials for the treatment of diabetes, obesity, and nonalcoholic steatohepatitis." (PMID 38879678, 2024). "Research indicates that the glucagon receptor antibody (anti-GCGR) has significant potential for promoting β-cell regeneration in diabetes models." (PMID 39057094, 2024). "More recently, studies have shown that inducible elimination of glucagon action by administration of a GCGR monoclonal antibody (GCGR-Ab) enhances beta cell survival, regeneration, and function in pre-clinical models of type 1 (T1D) and type 2 (T2D) diabetes." (PMID 39433176, 2024).
diabetes (continued). "This study supports the notion that glucagon and inhibition of glucagon receptor signaling can be used as a strategy to control hyperglycemia in diabetes." (PMID 37140984, 2023). "The role of glucagon dysregulation in diabetes is recognised, and glucagon receptor antagonists are already emerging as a promising new class of anti-diabetic drugs." (PMID 37159865, 2023). "Elevation in circulating glucagon level can be observed in patients with type 1 and type 2 diabetes, and excessive activation of GCGR promotes the progression of diabetes." (PMID 37596940, 2023). "In vivo studies have also shown that the reduction of GCGR expression benefits the treatment of diabetes." (PMID 37586587, 2023). "In this regard, development of structural and functional GCGR antagonists represents a potential approach to decrease hepatic glucose production and lower blood glucose in patients with diabetes." (PMID 37586587, 2023). "An inactivating antibody at the glucagon receptor reduced the incidence of diabetic cardiomyopathy in a mouse model of diabetes when given over several months." (PMID 37629010, 2023). "The glucagon receptor ranked among the lowest on the list with only one known disease-associated mutation, rs1801483/G40ECDS associating with diabetes, recorded in DisGeNET." (PMID 34801547, 2022). "As glucagon signaling plays a central role in glucose homeostasis and contributes to diabetes pathophysiology, there has been considerable interest in targeting the GCGR for treatment of diabetes." (PMID 36334626, 2022). "Blockade of GCGR by small molecule antagonists, antisense molecules, or antibodies can improve glycemic control in both rodent diabetes models and humans with diabetes." (PMID 36334626, 2022). "Approaches using GCGR antagonism and GCGR KO rodent animals have shown promising effects on glucoregulation in both type 1 and 2 diabetes." (PMID 36334626, 2022). "Increasing evidence indicates that blocking glucagon and glucagon receptor (GCGR) can relieve hyperglycemia in animals and humans, clearly establishing the important roles of glucagon and GCGR in the pathogenesis of diabetes." (PMID 35784565, 2022). "Our observations further support the promise of peptidic GCGR antagonists as a new class of drugs for the management of various forms of diabetes." (PMID 36005280, 2022). "It is reasonable to assume that even with GCGR mutations in β cells, glucagon binding to GLP-1R exerts an insulin-promoting effect that can reduce blood glucose concentrations in patients with diabetes." (PMID 35784565, 2022). "Further research on islet α cells, glucagon, and GCGR signaling pathways is expected to provide a basis for developing new strategies for diabetes prevention." (PMID 35784565, 2022). "More prolonged studies, including those in models of diabetes are required to investigate the long-term consequences of such prolonged exposure to GCGR and GLP-1R activation by OX-SR, but the peptide does represent a potential once-weekly OXM formulation." (PMID 34093449, 2021). "Other studies report drugs targeting the glucagon receptor, and glucagon receptor antagonists, as potential approaches to treat diabetes." (PMID 33839150, 2021). "The GCGR has been considered an important drug target in the treatment of type 2 diabetes mellitus (T2DM) due to its effect on pancreatic alpha-cells." (PMID 31405212, 2019). "This abnormal glucagon secretion has led to strategies to control glucagon action to ameliorate the hyperglycemia of diabetes, such as administering glucagon receptor antagonists or neutralizing antibodies against the glucagon receptor." (PMID 30713523, 2018). "Antisense oligonucleotides also improve HbA1C in people with diabetes in phase 2 clinical trials while monoclonal antibodies against the glucagon receptor reduce glucagon-induced glucose excursions." (PMID 29412829, 2018). "•Agents that block activity at the glucagon receptor are being used in clinical trials to treat diabetes." (PMID 29412829, 2018).